SMAD3 (SMAD family member 3)
Diseases named in the same sentence as SMAD3 in open-access papers (continued):
Sharing a sentence is not in itself a finding about the gene and the disease.
papilloma (3 papers, 2011 to 2021). A benign epithelial neoplasm that projects above the surrounding epithelial surface and consists of villous or arborescent outgrowths of fibrovascular stroma. "In contrast, SMAD3 knockout dramatically reduces the number of papillomas and cSCC tumors that form in response to DMBA/TPA, suggesting that SMAD3 promotes cSCC progression." (PMID 34553848, 2021). "When grafted onto nude mice, v-rasHa-transduced Smad3-/- keratinocytes developed papilloma and progressed to SCC, but v-rasHa-transduced Smad3+/+ keratinocytes only formed papillomas." (PMID 22204491, 2011). "The studies suggest Smad3 does not alter proliferation, but prevents malignant conversion of papillomas formed by engraftment onto nude mice." (PMID 22204491, 2011). "In two chemical carcinogenesis studies using Smad3+/− and Smad3−/− mice, it was found that in contrast to Smad2 deletion, Smad3+/− mice developed fewer tumors compared to wild-type controls; Smad3−/− mice also developed fewer papillomas than wildtype controls and did not progress to SCC." (PMID 23326666, 2012).
polycystic ovary syndrome (3 papers, 2024 to 2026). A disorder that manifests as multiple cysts on the ovaries. "Overexpression of SMAD3 in DevF2 also seemed to be related to GCs functional impairment and follicular atresia, as observed in GCs of women with polycystic ovaries, where its overexpression triggers apoptosis of GCs." (PMID 39468655, 2024).
preeclampsia (3 papers, 2019 to 2020). Preeclampsia is a hypertensive disorder of pregnancy that is characterized by new-onset hypertension with proteinuria presenting after 20 weeks of gestation, and depending on mild or severe forms may initially present with severe headache, visual disturbances, and hyperreflexia. "Collectively, our study suggests that the downregulation of LOX and LOXL2 leading to reduced trophoblast cell migration and invasion through activation of the TGF-β1/Smad3/collagen pathway is relevant to preeclampsia." (PMID 30804321, 2019). "The involvement of the TGF-β /SMAD3 pathway in regulating LOX expression was also confirmed in preeclampsia, a pregnancy-specific condition, in which decreased LOX was shown to be in close association with impaired trophoblast invasion in preeclamptic placenta." (PMID 32708046, 2020). "Thus, we proposed that LOX, LOXL2, and the TGF-β1/Smad3/collagen pathway can serve as potential markers and targets for clinical diagnosis and therapy for preeclampsia." (PMID 30804321, 2019). "Additionally, we detected that the TGF-β1/Smad3 pathway was induced in placentas from preeclampsia patients." (PMID 30804321, 2019). "Thus, our findings suggest that LOX, LOXL2, and the TGF-β1/Smad3/collagen pathway are potential markers and targets for clinical diagnosis and therapy for preeclampsia." (PMID 30804321, 2019). "There is consistent data to support TGF- β1/Smad3 signaling-driven LOX induction resulting in cellular fibrotic mechanism, multiple tissue fibrosis, ventricular remodeling and impaired trophoblast invasion in preeclampsia." (PMID 32708046, 2020).
prostate adenocarcinoma (3 papers, 2019 to 2025). "Specifically, ONECUT2 activates SMAD3, which regulates hypoxia signaling through moderating HIF-1α transcriptional binding, causing higher degrees of hypoxia in NEPC compared to prostate adenocarcinomas." (PMID 32509575, 2020). "Specifically, ONECUT2 activates SMAD3, which regulates hypoxia signaling through modulating HIF1α chromatin-binding, leading NEPC to exhibit higher degrees of hypoxia compared to prostate adenocarcinomas." (PMID 30655535, 2019).
renal carcinoma (3 papers, 2018 to 2022). A carcinoma arising from the epithelium of the renal parenchyma or the renal pelvis. "The lysates of human renal carcinoma (ACHN) cells were used to detect the degradation of recombinant Smad3 by PROTAC in vitro since ACHN cells contained very high pVHL protein level.Western blot results showed that the degradation of Smad3 was related to the amount of PROTAC." (PMID 36536448, 2022). "Taken together, As2O3 may play an anti-apoptosis role in renal cancer by up-regulating the expression of SMAD3 as well as the pathway crosstalk between TGF-β/SMAD3 and Wnt signaling pathway." (PMID 29633893, 2018). "In renal cancer, ICI 182,780 can block the ERβ/TGF-β1/SMAD3 signals pathway, thereby better inhibiting the progression of RCC14." (PMID 32409702, 2020).
systemic lupus erythematosus (3 papers, 2021 to 2024). An autoimmune multi-organ disease typically associated with vasculopathy and autoantibody production. "In comparison 4, Smad3+/− in db/db mainly increase the genes in the pathway of cell cycle, systemic lupus erythematosus, alcoholism, progesterone‐mediated oocyte maturation and oocyte meiosis." (PMID 33369170, 2021). "However, a much larger set of TFs contained in the TNF-α signaling gene set appeared among the active TFs in lupus cells; these include FOSL1, KLF6, RELB, BHLHE40, EGR3, and SMAD3." (PMID 39688922, 2024).
teratoma (3 papers, 2015 to 2017). A non-seminomatous germ cell tumor characterized by the presence of various tissues which correspond to the different germinal layers (endoderm, mesoderm, and ectoderm). "Although the histological studies showed that in Smad3−/− teratomas, all three germ layers were presented, neural tube like structures (rosettes) were lesser than the WT teratomas." (PMID 26905010, 2016). "In striking contrast to WT and Smad3−/− teratomas, Smad2−/− teratomas mainly had fibroblasts like tissues and within which scattered with few muscle tissues and endoderm tissues, while neural tube like ectoderm tissues were hardly presented." (PMID 26905010, 2016). "To further examine the correlation between Smad3 and Rif1, we examined the expression profiles of these two genes in mouse ESCs, mouse embryonic fibroblasts (MEFs), teratoma cells and mouse ESC-differentiated cells." (PMID 25569105, 2015). "It is speculated that decreased SMAD3 gene expression may be one of the reasons why teratomas are induced abnormally." (PMID 28257460, 2017). "Recently, it has been reported that SMAD3 is closely connected with teratoma formation from ESCs." (PMID 28257460, 2017). "Comparison of the expression of Smad3 and Rif1 between teratoma cells and teratocarcinoma cell lines F9 and P19 revealed that Smad3 was significantly lower in teratocarcinoma cells than teratoma cells, whereas Rif1 is significantly higher in teratocarcinoma cells than teratoma cells." (PMID 25569105, 2015). "We also investigated DEFB1, DEFB3, DEFB7, and SMAD3, which may be related to teratoma formation." (PMID 28257460, 2017).
ulcerative colitis (3 papers, 2023 to 2025). An inflammatory bowel disease involving the mucosal surface of the large intestine and rectum. "As Tc17 cells are involved in the pathogenesis of several inflammatory diseases in humans, we sought to determine whether the strong inverse relationship between Tc17 differentiation and SMAD3 expression applies in actual clinical settings, such as in ulcerative colitis (UC)." (PMID 38575593, 2024).
alcoholic liver diseases (2 papers, 2014 to 2021). A disorder caused by damage to the liver parenchyma due to alcohol consumption. "Furthermore, Sirtuin 6 (SIRT6), a NAD-dependent histone deacetylase which is a critical epigenetic regulator in alcoholic liver disease, deacetylates Smad family member 3 (Smad3) and attenuates its expression induced by transforming growth factor β (TGF-β) in the activated HSCs." (PMID 33791228, 2021).
Arthritis (2 papers, 2015 to 2018). Inflammation of a joint. "This was supported by the finding that loss of Smad7 was associated with a marked activation of TGF-β/Smad3 signaling and the development of arthritis in patients with RA." (PMID 30450102, 2018). "Further studies revealed that enhanced arthritis in Smad7 KO CD-1 mice was associated with increased Th1, Th2 and, importantly, Th17 over the Treg immune response with overactive TGF-β/Smad3 and proinflammatory IL-6 signaling in the joint tissues." (PMID 30450102, 2018). "For instance, the proteins TNFS10, SMAD3, ISG15 are annotated to increased susceptibility to induced arthritis, knee OA and abnormal bone ossification phenotypes respectively, suggesting the phenotype information complements the expression information." (PMID 25631385, 2015).
atopic asthma (2 papers, 2021 to 2022). An asthma that is characterized by symptoms that are triggered by an allergic reaction caused by inhaled allergens such as dust mite allergen, pet dander, pollen and mold. "Next, we confirmed that BMPR-II, SMAD3, and MRTF form a complex in our atopic asthma model, as evidenced by immunoprecipitation assays." (PMID 36008606, 2022).
brain cancer (2 papers, 2022 to 2024). A primary or metastatic malignant neoplasm affecting the brain. "HDAC2 activity regulates chromatin compaction that impacts the expression of SMAD3 and SOX2 and is, thus, critical for the self-renewal of brain cancer cells." (PMID 39063083, 2024).
Cachexia (2 papers, 2020 to 2021). Severe weight loss, wasting of muscle, loss of appetite, and general debility related to a chronic disease. "Interestingly, many of the cachexia associated genes such as FOXO1, FOXO3, SIRT1, SMAD3 and FABP3 were identified in age related gene expression in similar direction." (PMID 33923976, 2021).
cholestasis (2 papers, 2012 to 2021). Impairment of the bile flow caused by obstruction within the liver, or outside the liver in the bile duct system. "A remarkable finding noted in other data was that cholestasis induced TGFβ signaling via Smad3 in vivo." (PMID 22471627, 2012).
cholesteatoma (2 papers, 2015 to 2024). A pathologic process characterized by the proliferation of keratinizing squamous epithelium resulting in the accumulation of keratin and cells in the middle ear and/or mastoid. "Cholesteatoma pathogenesis is associated with decreased Smad3 expression, which is suggested to have pro-apoptotic functions." (PMID 39338148, 2024).
chronic asthma (2 papers, 2016 to 2021). An asthma that is characterized by the development of persistent airway inflammation and recurrent attacks of breathlessness and wheezing, which vary in severity and frequency. "TGFβ1/Smad3 is crucial in promoting airway remodeling in chronic asthma, and this phenomenon was also verified in this study." (PMID 34671356, 2021). "Accordingly, changes in the expression of TGFβ1/Smad3 and collagen I in the airways with acute and chronic asthma were detected via immunofluorescence." (PMID 34671356, 2021). "However, TGFβ1 and p-Smad3 expression slightly decreased in the OVA-induced chronic asthma compared with the acute asthma group." (PMID 34671356, 2021). "The mice with OVA-induced chronic asthma showed higher levels of inflammation and collagen deposition as well as SDC-1, p-Smad3, collagen I and α-SMA expression than the control group." (PMID 34671356, 2021).
cognitive deficits (2 papers, 2015 to 2026). "Here, we demonstrate that the TGF‐β1/Smad3 signaling pathway plays a critical role in regulating microglial phagocytic ability in removing Aβ and p‐tau aggregates, and more importantly, in reversing cognitive deficits during the advanced stage of AD." (PMID 41134085, 2026). "Mechanistically, deletion of Hrh4 in microglia, but not in neurons, reverses cognitive deficits and mitigates key AD pathogenesis by activating the cAMP/TGF‐β1/Smad3 pathway." (PMID 41134085, 2026).
crescentic glomerulonephritis (2 papers, 2021 to 2022). A histopathologic term for a pattern of diseases characterized by extensive crescent formation in the glomeruli; patients present clinically with rapid deterioration of renal function, and possible progression to end-stage renal failure within weeks or months. "Collectively, these data suggest that crescentic glomerulonephritis induced by anti-GBM serum in 129sv mice is SMAD3-dependent, underscoring the critical role of SMAD3 in the development of nephritis." (PMID 33669690, 2021). "Deletion of Smad3 in 129sv mice ameliorated anti-GBM induced nephritis, including crescentic glomerulonephritis." (PMID 33669690, 2021).
cystic fibrosis (2 papers, 2015 to 2017). Autosomal recessive disorder caused by pathogenic variants in the CFTR gene (cystic fibrosis transmembrane conductance regulator), which encodes a chloride and bicarbonate channel expressed in epithelial cells, and follow the diagnosis criteria. "Although, microRNA-145 has severally been shown to modulate Smad3 expression in some cell types including human chondrocytes and in some human diseases such as cystic fibrosis, however, how microRNA-145 modulates Smad3 in HCC remains unresolved." (PMID 29156696, 2017).
cystitis (2 papers, 2019 to 2025). Inflammation of the urinary bladder. "Three key proteins of the TGF-β/Smad pathway—TGF-β, p-Smad2, and p-Smad3—are upregulated in the bladders of CYP-induced cystitis rats (all P < 0.05)." (PMID 40271070, 2025).
dilated cardiomyopathy (2 papers, 2022). Cardiomyopathy which is characterized by dilation and contractile dysfunction of the left and right ventricles. "Whereas doxorubicin caused dilated cardiomyopathy in wild-type animals, inflammation, contractile decline, and left ventricular remodeling were prevented in Smad3-deficient mice." (PMID 36269647, 2022).
ductal breast carcinoma (2 papers, 2011 to 2021). "Furthermore, even though functional characterization of the role of Snail-Smad3/4 on the CAR promoter was conducted in mouse cells, in invasive human ductal breast carcinoma, nuclear expression of Snail, Smad3 and Smad4 correlated with loss of CAR expression at the invasive front." (PMID 21791114, 2011). "Overall, these data indicated that ductal carcinomas with high CCR2 expression were associated with increased invasiveness and increased expression of CCL2, phospho-SMAD3 and phospho-p42/44MAPK." (PMID 33888841, 2021).
echinococcosis (2 papers, 2022 to 2023). A parasitic infection caused by tapeworm larvae of Echinococcus. "The present study suggests that SMAD2 and SMAD3 have certain clinical relevance to hydatidosis in young children." (PMID 36443650, 2022). "The down-regulation of NF-κB also mediates the inhibition of the TGF-β1/Smad3 signaling pathway, which combined with the suppression of Th1-type cellular immunity, jointly promotes the progression of liver Echinococcosis." (PMID 38259969, 2023). "SMAD2 and SMAD3 have a certain clinical relevance with hydatidosis in young children." (PMID 36443650, 2022). "In addition, studies have shown that the NF- κB inflammatory signaling pathway and the TGF-β1/Smad3 fibrosis signaling pathway play a key role in regulating the immune-inflammation and fibrosis state of the host infected by Echinococcosis." (PMID 38259969, 2023). "The expression levels of TGF-β, SMAD2, SMAD3, SMAD4, and leukemia inhibitory factors (LIF) in the cystic fluid and the corresponding paracystal tissues of infected viscera or tissues in children with hydatidosis were measured using the ELISA kit." (PMID 36443650, 2022). "However, in patients with late chronic infection and relapse of Echinococcosis, the immune-inflammatory microenvironment shows weak expression, and the NF- κB and TGF-β1/Smad3 signaling pathways have interactions and crosstalk." (PMID 38259969, 2023).
encephalitis (2 papers, 2022 to 2024). An acute inflammatory process affecting the brain parenchyma. "Furthermore, the following genetic alterations were identified being associated with IRAE: SMAD3 (pancreatitis); CD274, SLCO1B1 (hepatitis); PRDM1, CD274 (encephalitis); PRDM1, CD274, TSHR, FAN1 (myositis)." (PMID 35053465, 2022).
endometritis (2 papers, 2022 to 2025). An acute or chronic, usually bacterial infectious process affecting the endometrium. "This study aims to elucidate how the TGF-β1/Smad3 signaling pathway regulates ECM remodeling in H2O2-mediated bovine endometritis." (PMID 40646747, 2025). "This implies that in bovine endometritis, the TGFβ1/Smad3 signaling pathway may play a dual role in ECM remodeling." (PMID 40646747, 2025). "Therefore, elucidating the regulatory mechanisms of oxidative-stress-mediated TGFβ1/Smad3 signaling on ECM remodeling is crucial for understanding the pathogenesis of endometritis." (PMID 40646747, 2025). "The results demonstrate that oxidative-stress-mediated endometritis significantly upregulates MMP2, MMP9, and the TGFβ1/Smad3 pathway activity, while suppressing COL-IV expression." (PMID 40646747, 2025). "This study found upregulated expressions of TGFβ1, Smad3, and MMP2/9 during bovine endometritis." (PMID 40646747, 2025).
esophageal cancer (2 papers, 2020 to 2025). A primary or metastatic malignant neoplasm involving the esophagus. "According to the results, 62.5% (10/15) of patients with esophageal cancer had SMAD3 hypomethylation." (PMID 33036415, 2020). "This indicates that SMAD3 is a specific biomarker in Taiwanese esophageal cancer." (PMID 33036415, 2020). "Therefore, further investigation to confirm the hypomethylation level of ccfDNA SMAD3 in esophageal cancer is encouraged." (PMID 33036415, 2020).
familial hypercholesterolemia (2 papers, 2023 to 2025). An inheritable form of hyperlipidemia, in which there are excess lipids in the blood. "A significant decrease in these cell signaling markers were observed following BMP-7 treatment, suggesting the efficacy of BMP-7 in attenuating hypercholesterolemia-induced TGF-β1, Smad2, and Smad3 proteins." (PMID 36829889, 2023). "Our data showed that, in diabetic mice, gene expressions of TGF-β1, Smad2, and Smad3 were significantly (p < 0.05) increased as compared with the control mice, suggesting a role of the TGF-β/Smad cell signaling pathway in hypercholesterolemia-induced pyroptosis and diabetic progression." (PMID 36829889, 2023).
fibroblastic tumor (2 papers, 2022 to 2023). "EWSR1::SMAD3–positive fibroblastic tumor (ESFT) is a benign neoplasm defined by a fusion of exon 7 of EWSR1 with exon 5 of SMAD3." (PMID 36983010, 2023).
gout (2 papers, 2016 to 2023). A condition characterized by painful swelling of the joints, which is caused by deposition of urate crystals. "Third, in the murine acute gouty arthritis model, qPCR-array and western blot analysis indicated that IL-1R8, Smad3 and S​OCS3 were highly expressed, whereas NLRP3 was suppressed in the rhIL-37 intervention groups." (PMID 27863506, 2016). "In addition, IL-37, an anti-inflammatory cytokine with an important role in gout, also functions via an interaction with SMAD3, a major intracellular signalling effector of TGF-β, further enforcing the importance of this signalling pathway in gout." (PMID 36850003, 2023).
head and neck cancer (2 papers, 2022 to 2024). A primary or metastatic malignant neoplasm affecting the head and neck. "Cetuximab in combination with SMAD3 inhibition to downregulate TGFβ in head and neck cancer." (PMID 36313650, 2022).
Hepatitis (2 papers, 2022 to 2024). Inflammation of the liver. "Further significant associations were as follows: HLA homozygosity (hepatitis), and VARs on SMAD3 (pancreatitis)." (PMID 35053465, 2022).